JAK2 (Janus kinase 2)
Diseases named in the same sentence as JAK2 in open-access papers (continued):
Sharing a sentence is not in itself a finding about the gene and the disease.
melanoma (continued). "Since the IFN-γ signaling pathway in melanoma cells induces tumor growth arrest and death, mutations of IFNGR1, IFNGR2, JAK1, JAK2, STAT1, and IRF3 lead to insensitivity to anti-tumor IFN-γ activity." (PMID 35432377, 2022). "A LHFPL3-AS1/miR-580-3p/STAT3 axis contributes to melanoma development by activating the JAK2/STAT3 pathway." (PMID 35132320, 2022). "In melanoma, the anti-tumor activity of brevilin A also depends on the status of JAK2/STAT3 pathway." (PMID 35818076, 2022). "Melanoma cell–secreted exosomal miR-155-5p activated the suppressor of cytokine signaling 1/janus kinase 2/signal transduction and activator of transcription 3 (SOCS1/JAK2/STAT3) signaling pathway and induced the proangiogenic switch of CAFs." (PMID 33869017, 2021). "ATL-1 was found to inhibit melanoma and colorectal cancer cell proliferation via the JAK2/STAT3 or AKT/mTOR signaling pathway." (PMID 34692516, 2021). "The same distribution was observed for sgRNAs targeting Jak1 and Jak2, which mediate the response to anti-PD-1 therapy in melanoma patients." (PMID 34853298, 2021). "In melanoma patients, loss-of-function mutations in IFN-gamma encoding genes or Janus kinase 1 (JAK1) and JAK2 are associated with acquired resistance to anti-PD-1 therapy." (PMID 34502043, 2021). "The results indicated that CD8A and SELL were up-regulated as well as JAK2 was down-regulated in melanoma samples compared with normal controls (p-value < 0.05)." (PMID 32316408, 2020). "The high expression of IRF1, JAK2, CD8A, STAT5B, and SELL was connected with a low risk of death and was a protective factor of melanoma." (PMID 32316408, 2020). "A previous study implicates the GH/GHR axis in inducing chemoresistance in human melanoma by JAK2/STAT5 activation." (PMID 32069380, 2020). "In melanoma, loss-of-function JAK1/JAK2 mutations were discovered in a minority of patients after relapse on the anti-PD-1 treatment pembrolizumab; therefore, it is a potential avenue of acquired resistance to immune checkpoint blockade." (PMID 30986992, 2019). "Mechanisms of acquired resistance to checkpoint inhibitors include loss of IFNγ-transducing signaling pathways JAK1 and JAK2, loss of antigen presentation (B2M) and activation of the PTEN/PI3K pathway in pembrolizumab-treated melanoma patients." (PMID 31647026, 2019). "Human melanoma cells MDA-MB-435 were incubated for 6 h with inhibitors of JAK2, STAT5, SRC, or ERK1/2 (p44/42-MAPK) at concentrations where they do not reduce cell viability by more than 20% in 24 h." (PMID 31547367, 2019). "The loss of SOCS1 expression leads to the activation of the JAK2/STAT3 signaling pathway and overexpression of MMP-2, FGF2, and VEGF and enhanced invasion and angiogenesis of melanoma cells, consequently promoting brain metastasis." (PMID 30285793, 2018). "In our study, treatment with melanoma cell-secreted exosomes significantly elevated the phosphorylation levels of JAK2 and STAT3 in CAFs." (PMID 30285793, 2018). "Our studies in the three melanoma patient models identified allelic JAK1 and JAK2 losses as initial genetic alteration predisposing to IFNγ-resistance development." (PMID 28561041, 2017). "Endocrine or paracrine as well as autocrine GH binds to abundantly expressed GHR on human melanoma and activates the JAK2 as well as SRC kinases." (PMID 28223541, 2017). "Chromosomal alterations and subsequent inactivating mutations in genes of the IFNγ signalling cascade, most often JAK1 or JAK2, protect melanoma cells from anti-tumour IFNγ activity." (PMID 28561041, 2017).
melanoma (continued). "These cytotoxic effects of BBMD3 are mediated through inhibition of the Jak2/STAT3 signaling pathway in melanoma cells and activation of the stress-response JNK pathway in osteosarcoma cells, respectively." (PMID 24732116, 2014). "In this study, we have discovered that the spirooxindole derivative SOID-8 inhibits melanoma cell proliferation and induces apoptosis of melanoma cells at least in part due to inhibition of the JAK2/STAT3 signaling pathway, in vitro and in vivo." (PMID 23166634, 2012). "Significantly, SOID-8 inhibits IL-6-induced STAT3 and JAK2 activation in melanoma cells, further supporting this notion." (PMID 23166634, 2012). "Our results indicate that the antitumor activity of SOID-8 is at least partially due to inhibition of JAK2/STAT3 signaling in melanoma cells." (PMID 23166634, 2012). "Both JAK1 and JAK2 knockout melanoma cells are insensitive to anti-PD-1 and anti-CTLA-4 therapy." (PMID 40108693, 2025). "By analyzing melanoma tumor biopsies that relapsed after PD-1 treatment, acquired homozygous loss-of-function mutations were identified in the kinases associated with the interferon-gamma receptor pathway: Janus kinase 1 (JAK1) and Janus kinase 2 (JAK2)." (PMID 38903504, 2024). "The melanoma cell‐secreted sEVs could activate CAFs through the elevation of the phosphorylation levels of JAK2 and STAT3 in CAFs." (PMID 37171030, 2023). "ATL II inhibits cancer cell proliferation and causes apoptosis primarily through regulating the PI3K/Akt, JAK2/STAT3, Ras/ERK, JNK/ERK-Nrf2-ARE, and LncRNA XIST/miR-30a-5p/ROR1 signaling pathways to treat colon, gastric, lung, melanoma, breast, and prostate cancers." (PMID 37241729, 2023). "Whole-exome sequencing of human melanoma tissues and the human melanoma cell line revealed that acquired resistance can result from loss-of-function mutations of IFNGR1, IFNGR2, JAK1, JAK2, STAT1, and IRF3 from the IFN-γ signaling pathway and β2M from antigen presentation pathway." (PMID 35432377, 2022). "Recently, crosstalk between MAPK and JAK2/STAT3 pathways in melanoma cells has been revealed." (PMID 34201116, 2021). "Similarly, melanoma patients, receiving anti–PD-1 therapy (pembrolizumab), developed immune escape lesions with LOH in JAK2 and a truncating mutation in B2M." (PMID 34680201, 2021). "Moreover, IRF1 and JAK2 had been reported as biomarkers of the anti-PD-1 immunotherapy response in melanoma via clinical sample validation." (PMID 32316408, 2020). "Although acquired mutations in Janus Kinase (JAK) 1, JAK2, and beta 2-microglobulin (B2M) are markers of resistance to PD-1 blockade in melanoma, their role in patients with CRC is not yet well defined." (PMID 32090113, 2020). "Whole exome sequencing of refractory melanoma tumor lesions of patients initially responding to anti–programmed death 1 (PD-1) therapy revealed loss-of-function mutations in the IFNyR-associated genes Janus kinase 1 (JAK1) and Janus kinase 2 (JAK2)." (PMID 31196219, 2019). "Additionally, an intriguing pre-clinical observation made in immune-competent mice challenged with melanoma demonstrates that acquired resistance to immune checkpoint blockade is reversed by inhibiting JAK1/JAK2 signaling." (PMID 30992475, 2019). "Structural alterations of JAK-2 in melanoma cells leading to reduced MHC class I APM expression and resistance to IFN-γ treatment were detected and overexpression of JAK-2 into JAK-2-deficient cells restored IFN-γ sensitivity and enhanced constitutive MHC class I surface expression in these cells." (PMID 29500634, 2018).
melanoma (continued). "Taken together, these results clearly suggest that the apoptotic effect of compound 1 in melanoma cells is due to inhibition of JAK2/STAT3 signaling leading to the activation of pro-apopotic regulators and the inhibition of anti-apoptotic regulators, rather than through a general toxicity mechanism." (PMID 28570563, 2017). "However, to our knowedge, few natural products act via JAK2 inhibition or have been investigated for the potential treatment of malignant melanoma." (PMID 28570563, 2017). "In this study, the authors show that melanoma patients can become resistant to immunotherapy by acquiring chromosomal alterations and subsequent inactivating mutations in genes of the IFNγ signalling cascade, most often JAK1 or JAK2." (PMID 28561041, 2017). "Therefore, we performed Western blots to determine the expression levels of JAK1 and JAK2 during the course of melanoma development." (PMID 25690042, 2015). "Accordingly, SOID-8 inhibited IL-6-induced activation of STAT3 and JAK2 in melanoma cells." (PMID 23166634, 2012). "Finally, SOID-8 suppressed melanoma tumor growth in a mouse xenograft model, accompanied with a decrease of phosphorylation of JAK2 and STAT3." (PMID 23166634, 2012). "A study analyzing 95 melanoma patients treated with ICIs found that genes affected by VARs associated with hypophysitis include SMAD3, PRDM1, and IL1RN, while genes affected by CNVs related to the occurrence of hypophysitis are TERT, SMAD3, JAK2, PRDM1, FAN1, CD274, and UNG." (PMID 41465179, 2025). "Furthermore, knocking out DENR in human cancer cell lines, such as human colon HT29 cancer cells and human melanoma A375 cells, also resulted in reduced JAK2 protein levels, indicating that the mechanism of DENR in regulating JAK2 expression is conservative in both murine and human." (PMID 35440133, 2022). "The acquired resistance to anti-PD-1 immunotherapy in melanoma tumors was found to be related to several mutations in genes encoding interferon receptor-associated Janus kinase 1 (JAK1) and Janus kinase 2 (JAK2), which could result in the insensitivity of tumor cells to IFN-γ." (PMID 32992737, 2020). "Acquired resistance to PD-1 blockade immunotherapy in patients with melanoma was associated with defects in the pathways involved in interferon-receptor signaling, such as mutation of interferon-receptor-associated Janus kinase 1 (JAK1) or Janus kinase 2 (JAK2)." (PMID 32310956, 2020). "Neither mutation nor gene expression change in JAK1, JAK2, B2M, HLA-A, HLA-B, and HLA-C was observed between pre- and post-treatment tumor samples, which were previously indicated to be associated with resistance to PD-1 antibody treatment in melanoma." (PMID 30872362, 2019). "An intriguing pre-clinical observation in an immune-competent melanoma model is that acquired resistance to ICI blockade could be overcome by inhibiting JAK1/JAK2 signalling, suggesting that JAK/STAT signalling may have a more complex role in mediating response and resistance to ICI." (PMID 29319049, 2018). "However, few JAK2 inhibitors were being tested for melanoma therapy." (PMID 28570563, 2017). "Melanoma-derived exosomal miR-155 downregulates suppressor of cytokine signaling 1 (SOCS1), an inhibitor of the JAK2/STAT3 pathway, activating JAK2/STAT3 signaling, promoting MMP-9 expression, and enhancing tumor angiogenesis." (PMID 40284474, 2025). "Previous studies have demonstrated that IFNγ-induced PD-L1 expression is reliant on JAK1/JAK2 activity, and that PD-L1 promoter activity and subsequent expression is mainly influenced by STAT1/STAT3 and IRF1 in IFNγ treated melanoma cells." (PMID 39736644, 2024). "MYC appeared to have a substantial influence on immunotherapy resistance by negatively affecting Janus Kinase 2 (JAK2) expression and the responsiveness of melanoma cells to IFN-γ." (PMID 38139110, 2023).
melanoma (continued). "The findings of this study are also in agreement with previous findings in which TQ treatment reduced the phosphorylation of JAK2 and STAT3, which consequently led to enhanced apoptosis in SK-MEL-28 melanoma cells." (PMID 37375831, 2023). "In melanoma, sEV‐miR‐155 induces the proangiogenic switch of CAFs by inhibiting SOCS1 expression and activating the JAK2/STAT3 signaling pathway." (PMID 37171030, 2023). "Truncating mutations, homozygous deletions, and low protein levels of IFNGR1, IFNGR2, JAK1, JAK2, STAT1, and IRF1 in melanoma patients result in shorter survival than that of patients with wild-type IFNγ signaling genes." (PMID 34385592, 2022). "In particular, the most studied and commonly altered pathways in melanoma are the mitogen-activated protein kinase (MAPK), PI3K, and Janus kinase-2/signal transducer and activator of transcription 3 (JAK-2/STAT3)." (PMID 35203404, 2022). "The results were also supported by the findings of a previous study in which TQ treatment reduced the phosphorylation of JAK2 and STAT3 in SK-MEL-28 melanoma cells." (PMID 36145344, 2022). "It has suppressed the expression of janus Kinase 2 (Jak2) and STAT3, as well as upregulated the ROS level, and promoted apoptosis in human melanoma cells." (PMID 35774546, 2022). "For example, melanoma cell-secreted exosomal miR-155-5p, which was selected as a survival-associated miRNA, could induce a proangiogenic switch of fibroblasts associated with cancer through improving proangiogenic factors' expression in recipient fibroblasts via SOCS1/JAK2/STAT3 signaling pathway." (PMID 33897771, 2021). "In summary, we conclude that CIRT can reduce the population of MDSC through a JAK2/STAT3-dependent signalling pathway, boost anti-tumour immune responses, and reduce tumour growth, therefore, increasing the overall survival of the melanoma-bearing mice." (PMID 34732697, 2021). "OSM is a cytokine belonging to the IL-6 family, and in the A375 human melanoma cell line, OSM receptor signaling is mediated by JAK1, JAK2, and tyrosine kinase 2 signaling via STAT3 and STAT5b." (PMID 34067095, 2021). "These are EGFR, ERRFI1, IL6, JAK2, PLXNC1, RGL3 which were found to be upregulated and CBL, CDC42, PIK3R3, STAT3, UBE2D2 and YWHAZ which were found to be downregulated; Melanoma has PLXNC1 as upregulated and TGFA as downregulated gene." (PMID 34764329, 2021). "Here, the use of carbon ion beams (5 GyE) for melanoma-bearing mice was found to reduce the population of MDSC in the bone marrow, peripheral blood, and spleen of the animals via a JAK2/STAT3-dependent mechanism." (PMID 34732697, 2021). "In addition, deletion of genes necessary for IFN-γ signaling (such as IFNGR1, IFNGR2, STAT1, JAK1, and JAK2) have been noted in pre-clinical models of melanoma that can lead to resistance to anti-PD-1/PD-L1 therapies, which might also play a role in acquired resistance." (PMID 33419311, 2020). "In conclusion, six hub genes (IRF1, JAK2, CD8A, IRF8, STAT5B, and SELL) were discovered to distinguish the response of melanoma patients under anti-PD-1 immunotherapy via WGCNA and integrated bioinformatics." (PMID 32316408, 2020). "Interestingly, short-term JAK2 inhibition in a preclinical melanoma model did not affect immunotherapeutic responses, while for melanoma patients inactivating JAK2 mutations have already been associated with a diminished response to anti-PD-1 directed immunotherapy." (PMID 31506076, 2019). "This did indicate that endogenous GH and the JAK2, STAT5, and SRC signaling pathways were critical for melanoma survival." (PMID 31547367, 2019). "In conclusion, our study demonstrates that melanoma cell-secreted exosomal miR-155 can trigger normal fibroblast reprogramming into proangiogenic CAFs by decreasing SOCS1, to activate JAK2/STAT3 signaling pathway." (PMID 30285793, 2018). "OC also inhibited the STAT3 upstream activator, Janus kinase 2 (JAK2), and Src kinase signalling in melanoma cell apoptosis." (PMID 29734791, 2018).
melanoma (continued). "In melanoma cells, STAT5 acts to mediate resistance to apoptosis and is reported to be activated by both JAK2 and SRC kinases." (PMID 28223541, 2017). "The JAK2/STAT3 signaling pathway plays a critical role in tumorigenesis, and has been suggested as a potential molecular target for anti-melanoma therapeutics." (PMID 28570563, 2017). "BBMD3, another JAK2 inhibitor, which inhibited autophosphorylation of JAK2 and blocked activation of downstream STAT3 signaling in melanoma cells." (PMID 28570563, 2017). "Suppression of p-JAK2 and p-STAT3 by SOID-8 in melanoma cells was observed in a time-dependent manner." (PMID 23166634, 2012). "Unlike in melanoma, our results highlight the important role of Jak2 and Stat1 in inducing PD‐L1 expression in HNSCC." (PMID 36515567, 2023). "ATL I inhibits cancer cell proliferation and induces apoptosis primarily by regulating the PI3K/Akt, JAK2/STAT3, TLR4/MyD88/NF-κB, Notch, and ERK/GSK3β signaling pathways to treat colon, gastric, lung, melanoma, ovarian, breast, bladder, leukemia, prostate, and cervical cancers." (PMID 37241729, 2023). "By blocking the JAK2/STAT3 signaling pathway, ATL I has also been demonstrated to decrease cell viability, induce apoptosis, and impede cell migration in human melanoma cells A375, as well as down-regulate the levels of STAT3 target genes Bcl-xL, MMP-2, and MMP-9." (PMID 37241729, 2023). "Taken together, IRF1, JAK2, CD8A, IRF8, STAT5B, and SELL may serve as predictive therapeutic biomarkers for melanoma and could facilitate future anti-PD-1 therapy." (PMID 32316408, 2020). "In addition, exosomal miR-155 derived from melanoma cells upregulated the expression of proangiogenic factors, such as VEGF, FGF2, MMP9, in CAFs by targeting SOCS1/JAK2/STAT3 signaling pathway, which resulted in the increase of melanoma angiogenesis." (PMID 32489584, 2020). "Certain genetic mutations in melanoma, including JAK1, JAK2, B2M and PTEN, etc., correlate with negative treatment response of PD-1 blockade therapy, while BRCA2 mutations were reported enriched in melanomas responsive to this treatment." (PMID 32333081, 2020). "Moreover, we found a statistically significant positive correlation between JAK2 and CCND2 expression in multiple types of cancer, such as melanoma, breast, lung, and renal cancer." (PMID 31511084, 2019). "The presence of basal phosphorylation of both JAK2 and SRC kinases as well as their respective changes with GHRKD and/or excess GH as observed in all cell lines, indicates that both signaling mediators to be highly responsive to GH in melanoma." (PMID 28223541, 2017). "However, less special drug for metastatic melanoma is approved for the first-line therapy.The Janus kinase 2 (JAK2)/signal transducer and activator of transcription 3 (STAT3) pathway is overactivated in many human cancers, including melanoma." (PMID 28570563, 2017). "We additionally found other routes of GH induced signaling downstream of JAK2 and SRC, including GH-induced increases in phosphorylation states of STAT5, STAT1, STAT3 as well as of AKT, mTOR, and ERK1/2 in all four human melanoma cell lines." (PMID 28223541, 2017). "The mechanism for this is likely due to the dual inhibition of phosphorylated forms of JAK2 and STAT3 thereby reducing STAT3 transcriptional activity, as has been shown for several cancer cell lines including glioma, myeloid leukemia, and melanoma." (PMID 24804649, 2014). "Our data shows that SOID-8 reduced tyrosine phosphorylation of STAT3 in both dose- and time-dependent manners, and this suppression was mediated through decreased levels of phosphorylation of JAK2 but not c-Src in A2058 and A375 melanoma cells." (PMID 23166634, 2012).